PDCD4 (programmed cell death 4)
Diseases named in the same sentence as PDCD4 in open-access papers (continued):
Sharing a sentence is not in itself a finding about the gene and the disease.
tumor (continued). "MiR-21, known for its abundant expression, plays a significant role in carcinogenesis by targeting two tumor suppressors: TPM1 and programmed cell death-4 (PDCD4)." (PMID 38398227, 2024). "miR-21 is predominantly an oncomiR, promoting tumorigenesis by inhibiting tumour suppressors such as PTEN and PDCD4, and facilitating invasion, metastasis, and chemoresistance." (PMID 39456841, 2024). "Programmed cell death 4 (PDCD4) is a known suppressor of tumorigenesis, tumor progression, and invasion, functioning both independently and in response to external stimuli." (PMID 39114567, 2024). "MiR-21 exerts its oncogenic functions by targeting genes like TPM1, PDCD4, PTEN, and Smad7, enhancing tumor cell growth and inhibiting apoptosis." (PMID 38726321, 2024). "Programmed cell death 4 (PDCD4), a tumor suppressor, is a binding protein of eukaryotic initiation factor 4 A (eIF4A), which inhibits translation." (PMID 38365838, 2024). "This miRNA targets several tumor suppressor genes, including PTEN and PDCD4, both of which are involved in apoptosis and cell cycle regulation." (PMID 39594601, 2024). "Conversely, ectopic expression of Pdcd4 cDNA in promotion-sensitive JB6 cells results in the development of a promotion-resistant phenotype and suppression of tumor growth." (PMID 39459035, 2024). "As, Cr, and Ni can upregulate miR-21, promoting angiogenesis and increasing the cell invasive potential, and can directly downregulate programmed cell death 4 (PDCD4), as a tumor suppressor." (PMID 38473984, 2024). "The down‐regulation of PDCD4 and PTEN was closely related to the high survival rates of tumor cells in the tumor environment." (PMID 36925699, 2023). "For instance, pro-tumor miR-21, which targets tumor suppressor genes such as PTEN, PDCD4, and RECKS, is elevated in arsenic-exposed lung cells." (PMID 37631277, 2023). "In HCC cells, miR-21 simultaneously regulates multiple programs that enhance tumor invasiveness by targeting PTEN, RECK, and PDCD4." (PMID 38139236, 2023). "Among the miRNAs found, miR-21 is currently identified as an ’oncomiR’ that targets several key tumor suppressor genes, such as PTEN and PDCD4, including the last one in ACC." (PMID 37372400, 2023). "The target genes of miR-21 include PDCD4, SMAD7, PTEN, HIF-1α, KRIT1, and other tumor suppressor genes." (PMID 37316504, 2023). "The programmed cell death 4 (PDCD4), a tumor suppressor with downregulation in various tumor types, induces cell apoptosis and inhibits the aggressive phenotype of cancer cells." (PMID 38001121, 2023). "Strikingly, multiple studies showed that miR-21 targets important tumor suppressor genes as well as genes involved in carcinogenesis, such as PTEN, PDCD4, and RECK." (PMID 37490255, 2023). "For example, miR-21-5p enhances tumor progression by targeting genes, such as leucine zipper transcription factor like 1 (LZTFL1), programmed cell death 4 (PDCD4), and tropomyosin 1 (TPM1)." (PMID 36768298, 2023). "Programmed cell death 4 (PDCD4), a tumor suppressor, suppresses TFEB translation in a eukaryotic initiation factor 4A-dependent manner." (PMID 35625599, 2022). "Programmed cell death 4 (PDCD4) is a common tumor suppressor and has been shown to be closely related to tumor development." (PMID 35295323, 2022). "The screened candidates, as the targets of miR-21 and miR-21*, included a large number of oncogenic proteins and tumour suppressors, such as Ras, GRHL3, CHL1, PDCD4, PTEN, RECK and HNRPK." (PMID 35421166, 2022). "CRC tumours and CRC cell lines (SW480, SW620, HT-29, HCT-116) were found to have increased expression of miRNA-503 and down-regulated PDCD4 mRNA when compared to healthy surrounding tissue and normal colon epithelial FHC cells." (PMID 35847932, 2022).
tumor (continued). "Programmed cell death 4 (PDCD4), a known tumor suppressor, can bind with eIF4A by blocking the binding between eIF4A and eIF44G or suppressing eIF4A helicase activity, resulting in impaired translation." (PMID 35879299, 2022). "Knockdown of PDCD4 in MKN-45 cells resulted in decreased apoptosis, whereas overexpression increased programmed cell death, confirming the role of the tumour suppressor as being pro-apoptotic." (PMID 35847932, 2022). "It is defined as one of the “oncomiRs”, the cancer-promoting miRNAs, and has been documented to target several tumour suppressor genes (such as PTEN, RHOB, PDCD4, TIMP3) and play a role in signalling pathways (RAS/MEK/ERK, PTEN/PI3K/AKT, and Wnt/β-catenin)." (PMID 36140324, 2022). "Known targets of miR-21 include SERPINB5 (also known as maspin) and PTEN, along with tumor suppressors TPM1 (tropomyosin 1) and PDCD4 (programmed cell death 4 protein)." (PMID 36010971, 2022). "This showed a direct relationship between miRNA-181b and PDCD4 in SW480 cells, which had direct consequences on tumour progression in vivo." (PMID 35847932, 2022). "MiR-21-5p has been previously reported to regulate chemosensitivity to classic BC treatment regimens by targeting tumor-suppressors such as PTEN and programmed Cell Death 4 (PDCD4) in various cancers." (PMID 36293478, 2022). "In silico investigation showed that both the tumour repressors Forkhead box protein O4 (FOXO4) and PDCD4 are candidate targets of miRNA-499-5p and direct binding of miRNA499-5p to 3’-UTR of the mRNAs was confirmed using luciferase assays." (PMID 35847932, 2022). "In contrast, miR-21, which is the most well-known oncogenic miRNA, acts as a negative regulator of the tumour suppression gene programmed cell death 4 (PDCD4), which normally inhibits cell proliferation and induces apoptosis, thus promoting tumour growth." (PMID 35805007, 2022). "Exosomal miR-106b found in colorectal cancer also suppresses PDCD4 driving both IL-6/STAT3 and mTOR signalling to promoting regulatory polarization in tumor macrophages." (PMID 35320943, 2022). "Two main targets of miR-21 are programmed cell death 4 (PDCD4) and phosphatase tensin homolog (PTEN), which induce apoptosis and repress tumor progression, respectively." (PMID 35955412, 2022). "miR-21 stimulates proliferation of BC cells and inhibition of apoptosis via suppressing tumor suppressors like PTEN, tropomyosin α1 (TPM1), and programmed cell death protein 4 (PDCD4)." (PMID 35392236, 2022). "This miRNA reduced the expression of Programmed cell death 4 (PDCD4), a suppressor of tumourigenesis and tumour progression, by expressing IL-6 in PCa cells." (PMID 35629050, 2022). "The bioinformatics analysis suggested that multiple tumor-related genes, including FoxO1, PTEN, and PDCD4 genes, have miR-21 binding sites." (PMID 36180486, 2022). "Overall, the result of their research showed that circ-ITCH serves as a tumor suppressor in OSCC partly by suppressing cell proliferation and Inducing apoptosis in OSCC by regulating miR-421/PDCD4 Axis." (PMID 35898889, 2022). "The PI3K/AKT, STAT3, and PDCD4/TNF-α signaling networks, regulated by the microRNA (miR)-21, are critical for inflammatory regulation, tumor suppressor modulation, and oncogenic activation." (PMID 34771727, 2021). "Programmed cell death 4 (PDCD4), a tumor suppressor, is firstly clarified as a gene that induces apoptosis in murine cell line." (PMID 33969128, 2021). "It is worth highlighting that miR-21 targets some common tumor-suppressor genes, such as PTEN or PDCD4." (PMID 34947804, 2021). "These two findings suggest that the decrease in PDCD4 immunostaining we observed in spleen cells of curcumin-treated rats vs. untreated rats might reflect the reversal produced by curcumin treatment on the deleterious effects induced by the tumor development on immune cell functions." (PMID 34445271, 2021).
tumor (continued). "Programmed cell death protein 4 (PDCD4) is an RNA-binding tumor suppressor protein that is vital for inhibiting carcinogenesis, tumor progression and invasion." (PMID 34917890, 2021). "Downregulation of RECK, PTEN, and PDCD4 due to the over-expression of miR-21 in HCC results in high levels of MMPs, which facilitate tumor progression and metastases." (PMID 34066762, 2021). "Akt and p70S6K are activated by the tumor promoter 12-O-tetradecanoylphorbol-13-acetate (TPA) and are required for the degradation of PDCD4." (PMID 34885115, 2021). "Functional assays demonstrated that miR-21 sequestering leads to up-regulation of miR-21 tumor suppressor targets (i.e., PTEN and Pdcd4), reduction in cancer cell migration, reduction in proliferation, and increase in cell death." (PMID 33414439, 2021). "In previous studies, we also observed that miR-133a-3p, miR-5188, miR-3188, miR-374a, and miR-296-3p, respectively were modulated by VPS33B, HBx, FOXO1, PDCD4, and HDGF involving in the tumor pathogenesis induced by these genes." (PMID 32641685, 2020). "miR-21 activates the EGFR/AKT signaling pathway via targeting tumor suppressor genes such as PTEN, PDCD4, APAF1, TPM1, TIMP3, RECK, FOXO1 and SPRY240." (PMID 32019988, 2020). "The NATs such as PDCD4-antisense RNA1 (PDCD4-AS1) are responsible for TNBC progression, which positively regulates the tumor suppressor, sense protein-coding partner PDCD4 (programmed cell death 4) expression in a cis manner." (PMID 32575858, 2020). "MiR-21 was responsible for the inhibition of anti-metastatic genes, such as PTEN, PDCD4 (Programmed Cell Death protein 4), and SPRY2 (Sprouty Homolog 2), promoting tumor migration." (PMID 31952362, 2020). "The mitogens, known as tumor promotors, EGF (epidermal growth factor) and TPA (12-O-tetradecanoylphorbol-13-acetate) stimulate the degradation of PDCD4 protein." (PMID 31952347, 2020). "The up-regulation of miR-21 promotes tumor invasion and metastasis by negatively regulating the expression of tumor suppressor genes such as PTEN and PDCD4." (PMID 31557962, 2019). "Thus, in the inflammatory areas, inflammatory cytokines downregulated PDCD4-protein levels in surrounding cells via NF-κB-miR21 and/or STAT3-miR21 axis and by the degradation of the protein resulting in high-risk environmental conditions for tumor promotion and carcinogenesis." (PMID 31075975, 2019). "It was shown that the methylation of PDCD4 at 110R by arginine methyltransferase 5 (PRMT5) increased the PDCD4 levels, tumor cell growth and viability in a nutritional deprivation condition." (PMID 31075975, 2019). "HBx-induced upregulation of miR-21 by Il-6 mediated STAT3 signaling typically blocks tumor suppressors like PTEN and PDCD4 at an early stage in the inflammation–fibrosis axis and continues in the HBV-HCC stage (pathway 14)." (PMID 31771261, 2019). "The conditional medium of the activated macrophages downregulated PDCD4-protein levels, activating the PI3K-Akt-mTOR-S6K signaling pathway and phosphorylating PDCD4-protein in various tumor cells." (PMID 31075975, 2019). "It was shown that PDCD4 interacts with Sp1 and Sp3 inhibiting the u-PAR expression and tumor invasion/intravasion." (PMID 31075975, 2019). "Our study showed PDCD4 is a novel ubiquitination substrate of SKP2, which helps to clarify SKP2 tumor promotion and DNA damage response action." (PMID 30760284, 2019). "miR-21 has been identified to target at the tumor suppressing genes, such as the protein tyrosine phosphatase (PTEN), programmed cell death 4 (PDCD4), and B cell translocation gene 2 (BTG2)." (PMID 31032345, 2019). "Viral oncoprotein Meq binds to transcriptional factor AP-1 to upregulate gga-miR-21 expression, targeting chicken programmed cell death 4 (PDCD4) and promoting tumor cell growth and apoptosis escape." (PMID 31683847, 2019).
tumor (continued). "In support, tumor samples harvested from the combination of pacritinib and TMZ showed the lowest level of STAT3, Sox2, PDCD4, and miR-21-5p and an increased level of GFAP." (PMID 31269723, 2019). "This is of translational relevance, considering that miR-21 is a well-established oncogenic miR whose major targets include the tumor suppressors PTEN and PDCD4, both of which inhibit PI3K/AKT/mTOR signaling and the Wnt/β-catenin cascade." (PMID 31878245, 2019). "MiRNA-21 is another BC-related miRNA that promotes in-vitro and in-vivo tumour growth by targeting PTEN and TPM1 tumour-suppressor genes, whereas it affects metastasis by directly targeting TIMP3, SERPIN5B, PDCD4 and BCL28,9." (PMID 31811234, 2019). "Function analysis discovered that miR-196a overexpression or PDCD4 knockdown promoted proliferation and induced apoptosis in CRC cells, however, the pro-tumor effect of up-regulated miR-196a or down-regulated PDCD4 was reserved by Linc00472 overexpression." (PMID 29930217, 2018). "Both PDCD4 and BTG2 are described to play a tumor suppressor role in several cancers and are downregulated in PDAC." (PMID 29464088, 2018). "miR-21 exerts its activity by regulating numerous aspects of the tumorigenesis process, notably through the regulation of numerous tumor suppressor genes including PTEN, PDCD4 and CDKAP1." (PMID 30286096, 2018). "Mechanistically, it has been described that overexpression of miR-21 leads to the inhibition of several tumor suppressor genes, such as PTEN, TPM1 and PDCD4." (PMID 28915579, 2017). "In this study, we proved that miR-19a inhibits TIA1 to indirectly downregulate PDCD4, which is a TIA1 target as well as an important tumor suppressor in CRC." (PMID 28257633, 2017). "miR-21, for example, targets the tumor suppressor genes PTEN (Phosphatase and Tensin Homolog) and PDCD4 (Programmed Cell Death 4) in several neoplasms." (PMID 28704968, 2017). "Its target, programmed cell death protein 4 (PDCD4), normally acts as a tumour suppressor by inducing apoptosis via a caspase cascade." (PMID 28895916, 2017). "It has also been reported that miR-21 promotes cell migration and invasion by targeting the PDCD4 (Programmed Cell Death Protein 4) and PTEN (phosphatase and tensin homolog) tumor suppressor genes." (PMID 28573140, 2017). "Among upregulated miRNAs, miR-21 and miR-499 were found to suppress the programmed cell death protein 4 (PDCD4), a tumor suppressor protein that is lost in the majority of tonsil SCC." (PMID 29209433, 2017). "The miR-21 also promotes tumor cell invasion and metastasis in metastatic breast cancer MDA-MB-231 cells by inhibiting the expression of PDCD4." (PMID 28423589, 2017). "Alternatively, it has been proposed that miR-21 downregulates expression of programmed cell death 4 (PDCD4) and tissue inhibitor of metalloproteinase (TIMP3), both of which function as tumor suppressors." (PMID 29069873, 2017). "PDCD4, NKX2-1 and PRKAA1 (AMPKA1) are well known tumor supressor genes, and our result suggests that DTL downregulates these genes." (PMID 28336923, 2017). "In addition, we investigated the biological effects of PDCD4 inhibition by miR-181b both in vitro and in vivo and found that miR-181b could promote cell proliferation and migration and suppress apoptosis in CRC cells and accelerate tumor growth in xenograft mice, potentially through targeting PDCD4." (PMID 27647131, 2016). "Previously, we reported that programmed cell death 4 (PDCD4), a tumor suppressor, negatively regulated autophagy in tumor cells." (PMID 26775706, 2016). "Several potential miR-21 targets have been identified including some tumor suppressor genes such as phosphatase and tensin homolog (PTEN), tropomyosin 1 (TPM1) and programmed cell death 4 (PDCD4)." (PMID 26862856, 2016).
tumor (continued). "The function of miR-21 has been well established because it is up-regulated in nearly all types of cancers and target tumor suppressor genes PTEN and PDCD4." (PMID 26646696, 2016). "Previous work showed that miR-21 can promote tumor spread by upregulating the expression of phosphatase and tensin homolog (PTEN), programmed cell death 4 (PDCD4) protein, and reversion-inducing cysteine-rich protein with Kazal motifs (RECK)." (PMID 27793160, 2016). "To investigate the effect of HIF-2α on the expression of Bak, ZBP-89 and PDCD4 in vivo, we detected the expression of HIF-2α, Bak, ZBP-89 and PDCD4 in xenograft tumor tissues by real-time PCR, western blotting and immunohistochemical staining analysis." (PMID 27119229, 2016). "In this study, we found that miR-181b, as an IL-6/STAT3-activated miRNA, directly targets PDCD4 to promote CRC cell proliferation and migration and to inhibit apoptosis in vitro and accelerate tumor growth in vivo." (PMID 27647131, 2016). "It is shown that miR-21-5p directly target the tumor-suppressor PTEN, chemokine gene CCL20 and PDCD4." (PMID 26462034, 2015). "It targets the tumor suppressor genes PTEN, Tropomyosin alpha-1 chain (TPM1) and Programmed Cell Death 4 (PDCD4), thereby exhibiting oncogenic activity by promoting tumor cell proliferation and inhibition of apoptosis." (PMID 25886191, 2015). "Cells exposed to ROS would up-regulate miR-21, which can directly interact with the 3′UTR of the programmed cell death 4 (PDCD4) gene, a known tumor suppressor and apoptosis-regulator, thereby preventing cell death." (PMID 26283969, 2015). "Three major targets of miR-21 include prominent tumor suppressors such as PTEN (phosphatase and tensin homolog), an important regulator of cardiovascular disease, PDCD4 (programmed cell death 4) and TPM1 (tropomyosin 1)." (PMID 29056711, 2015). "For example, miR-21 has a role not only in tumor growth, but also in invasion and tumor metastasis by targeting multiple tumor/metastasis suppressor genes such as TPM1, PDCD4 and Maspin in metastatic breast cancer." (PMID 26694467, 2015). "While miR-21 has been found to promote tumour proliferation and invasion in GC by negatively regulating important tumour suppressors such as PTEN, PDCD4, and RECK, and then confer GC cells with increased invasiveness and the ability to avoid anoikis." (PMID 24614175, 2014). "MiR-21 functions as an oncogenic microRNA by targeting multiple tumor suppressor genes including PTEN, PDCD4, BCL-2, TPM1, and RECK, and its participation has been reported in many human cancers." (PMID 25428915, 2014). "In conclusion, the present study demonstrated that miR-21 downregulates the expression of PDCD4 and PTEN, and that the inhibition of miR-21 suppresses tumor growth and invasion." (PMID 24959246, 2014). "Despite the limited number of ESCC cell line and clinical samples employed in our study, we have successfully and experimentally replicated that miR-21 promotes tumour growth and migration in ESCC through directly repressing PDCD4." (PMID 25400316, 2014). "Another widely expressed miRNA in hematopoietic and solid tumors is miRNA-21 miR-21 targets several tumor suppressor genes such as phosphatase and tensin homolog (PTEN), programmed cell death 4 (PDCD4), and tropomyosin 1 (TPM1)." (PMID 26056576, 2014). "PDCD4 is a proapoptotic molecule involved in the TGF-β1-induced apoptosis in human HCC cells and a possible tumor suppressor in hepatocarcinogenesis." (PMID 25364579, 2014). "MiR-21 targets tumor suppressor genes, such as phosphatase and tensin homolog (PTEN), tumor suppressor gene tropomyosin 1 (TPM1), programmed cell death 4 (PDCD4), maspin, and reversion-inducing cysteine-rich protein with Kazal motifs (RECK)." (PMID 25243154, 2014). "miRNA microarray analysis has revealed that miR-21 was dramatically elevated in HCC tumor cells, with significant reductions of the expressions of several tumor suppressor genes, including PTEN, PDCD4, RECK and TPM1 (PTEN)." (PMID 24112539, 2013).